CD14 (CD14 molecule)
Diseases named in the same sentence as CD14 in open-access papers (continued):
Sharing a sentence is not in itself a finding about the gene and the disease.
tumor (continued). "Furthermore, analysis of 366 HCC tumor samples from TCGA demonstrated positive associations of tissue CRP level and genes related to myeloid cells, including CD68 and CD14, as well as chemokines and receptors for the chemotaxis of monocytes or neutrophils, such as CCL2, CCR2, and CXCL1." (PMID 35070979, 2021). "Moreover, immunohistochemical staining showed that the infiltration of CD45 labeled leukocytes in tumor increased under AQB treatment, while the infiltration of CD14 labeled macrophages decreased, as well as the small amount of perforin and granzyme B staining was present in the tumor portion." (PMID 34887871, 2021). "However, after adjusting for hrHPV status, myeloid marker densities in the IT Tumor compartment were no longer significantly associated with survival (CD14 p = 0.65, CD68 p = 0.96, CD163 p = 0.53)." (PMID 34194435, 2021). "Therefore, our study revealed that the antitumor response of the host may be defective due to the decreases in total monocyte and CD14+ monocyte levels in tumor tissue." (PMID 32131750, 2020). "Another subset of circulating and tumor-associated monocytes endowed with proangiogenic activity, are characterized by the expression of the TIE-2/Tek angiopoietin receptor, Endoglin and VEGF-R2 in the intermediate monocytes subset (moM2, CD14++/CD16+) as confirmed by a genomic analysis." (PMID 33108409, 2020). "CD14+ monocytes are usually positive selected using immunomagnetic beads, then differentiated through controlled supplementation of cytokines; obtained immature DC are loaded with tumor antigens and finally stimulated to mature by exposure to inflammation cocktail." (PMID 32131407, 2020). "Therefore, the authors concluded that tumour induced factors led to the low HLA-DR expression in the monocyte phenotype, however, Dex reduced CCL2 secretion by the tumour, reducing tumour recruitment of monocytes and resulting in increased peripheral CD14+HLA-DR−/lo monocytes." (PMID 31973059, 2020). "The cell types and markers we explored were as follows: tumor epithelial cells (E-cadherin as a marker), cancer-associated fibroblasts (CAFs; Collagen1A1), endothelial cells (Von Willebrand Factor [VWF]), the immune compartment (CD45), T cells (CD3G), myeloid cells (CD33), and macrophages (CD14)." (PMID 31765370, 2019). "Therefore, the reduction in intermediate monocytes present in GBM patients, coupled with the simultaneous increase in CCR2 expression in this cell subset, suggests the possibility that CD14+/CD16+ monocytes represent the cell subset actively recruited to the tumor in GBM patients." (PMID 30813960, 2019). "Therefore, the CD11c+HLA-DR+CD14−CD1c−CD141− “DN” cell population which constituted 0.5% of the leukocytes in tumor may contain either CD1c−CD141− mDCs or CD14− macrophages (or both)." (PMID 30774636, 2018). "Additionally, PF-04136309, a small molecule CCR2 inhibitor, depletes CCR-2+/CD14+ monocytes and macrophages from the primary pancreatic tumor and premetastatic liver resulting in enhanced anti-tumor immunity, decreased tumor growth, and reduced metastasis in mice model." (PMID 27191744, 2016). "In summary, our data suggest that an increased in the frequency of CD14+CD169+ cells may be associated with the development and progression of CRC and is concomitant rise of both pro-tumor (M2-like, IL-10 producing) and anti-tumor (M1-like, IL-12 producing) monocytes and infiltrating macrophages." (PMID 26509874, 2015). "Indeed, the majority of CD14+ leukocytes in the tumor microenvironment expressed pSTAT3." (PMID 24652403, 2014). "However, other tumor-derived factors may account for the higher number of intermediate (CD14++CD16+) monocytes observed in cancer patients." (PMID 22973451, 2012). "A large proportion of CD8+ T cells and CD14+/CD16+ monocytes belonged to EIM, and more immunofluorescent signals of CD8, CD14, and CD16 were detected in tumours from older relative to younger patients." (PMID 41502040, 2026).
tumor (continued). "It further converts immature (CD101-) and mature (CD101+) neutrophils into a CD14+ICAM-1+ subset through STING-NF-κB-TNF-α signaling, enhancing tumor infiltration and antitumor activity." (PMID 41854362, 2026). "To accurately characterize tumor cells within the HGSC microenvironment, we applied a stringent gating strategy to exclude immune (CD45+, CD33+, CD14+) and stromal (CD90+, CD140a+) components." (PMID 40877861, 2025). "In this study, we showed that RCC tumor cells express significant levels of lymphoid proteins, such as CD45RA, CD14, CD16, and CD56." (PMID 40440354, 2025). "The canonical markers EPCAM and KRT19 identified tumor cells, while CD3D, CD2, PTPRC, CD14, AIF1, CD79A, and COL1A2 validated non-tumor cells." (PMID 39955556, 2025). "Recent studies have highlighted a subset of CD8+ T-cells that express CD14 and may play an immunomodulatory role, particularly in response to chronic inflammation or persistent antigen exposure, such as during hepatic viral responses and tumor infiltration in cancer." (PMID 41148820, 2025). "The results revealed a significant increase in the protein levels of CD163, CD14, and CD68 in the tumor tissue compared to adjacent tissue (p < 0.0001)." (PMID 40270962, 2025). "Canonical markers were used to annotate different cell types: malignant cells (COL1A1, IBSP), myeloid cells (CD74, CD14), osteoclasts (CTSK, MMP9), pericytes (RGS5, ACTA2), endothelial cells (PECAM1, VWF), and tumor-infiltrating lymphocytes (CD3D, NKG7)." (PMID 40730548, 2025). "Seven patients in the testing group exhibited lymphatic tumor emboli in primary cancer, and these patients displayed decreased CD3+CD8+ cells and increased CD11b+CD14+/CD33+CD14+ M‐MDSC levels." (PMID 39749673, 2025). "The protein levels of macrophage-related genes, including CD163, CD14, and CD68, were assessed using immunohistochemistry (IHC) on tumor tissues and adjacent tissue microarray." (PMID 40270962, 2025). "Four malignant subclusters in the untreated sample MC3P1 exhibited limited interactions with immune cells, whereas those in the progressed tumor MC3P2 showed increased interactions, particularly with CD14+ Mono cells via BAFF signaling." (PMID 40876452, 2025). "In RCC, tumor cells acquire immune surface proteins such as CD14, CD16, CD56 and CD45 from infiltrating lymphocytes and monocytes, that promotes tumor survival by impairing immune effector function." (PMID 41181711, 2025). "In contrast, CD14+ monocytes and CD163+ and CD68+ macrophages predominated in the immune landscape of the FGF23-secreting tumour microenvironment, accounting for 30.74%, 23.23%, and 16.96% of all detectable immunopositive tumour cells, respectively." (PMID 40981193, 2025). "RCN6 was mainly localized in tumor stroma, where CAF-FAP was spatially proximal to t_MP5, CD8_PDCD1, neutrophil, Monocyte_CD14, and Macrophage_CXCL10, which featured by inflammation and immune exhaustion." (PMID 39870619, 2025). "Our single-cell and spatial transcriptomic analyses revealed that STX7 is predominantly expressed in monocyte-derived macrophages in HCC, with dynamic upregulation during differentiation and co-localization with CD14 and CD68 in tumor regions." (PMID 40999361, 2025). "Using tumor‐derived PGE2 from A375 CM, the addition of aEP2 or aEP2/4 downregulated CD163, MerTK, and CD14 expression, which indicates a less suppressive macrophage phenotype." (PMID 41211769, 2025). "We generated human M2 macrophages from blood derived CD14 + monocytes and co-cultured them with either CD20 + Raji tumor cells or MUC16 + SKOV3 tumor cells that were both transduced with FireFly Luciferase for measurement of tumor cell viability." (PMID 40408355, 2025). "Lidocaine suppressed IL-10 secretion in CD14+ tumor-infiltrating macrophages and CD4+CD25+ tumor-infiltrating Tregs." (PMID 40244064, 2025).
tumor (continued). "The tumor infiltrates marked by CD8A and CD14 were then explored as markers representing CTL and TAMC, because they were demonstrated to be their specific markers by scRNA analysis in CRC, respectively." (PMID 38557819, 2024). "To summarise, our study provides insights into the composition of immune cells within tumours in NSCLC and emphasises the presence of CD14+APOE+ cells and MMP7+ tumour cells in close proximity as significant factors in immune exclusion." (PMID 39187937, 2024). "The increased presence of myeloid-derived suppressor cells (MDSCs), in metastatic UVM, as identified by CD11b, CD14, and CD33, underscores their potential role in facilitating tumor progression and immune evasion." (PMID 39916959, 2024). "We observed that CD14+APOE+ cells were prominently represented in samples with immune exclusion, exhibiting a strong correlation with MMP7+ tumour cells." (PMID 39187937, 2024). "The co‐location of CD14+APOE+ cells and MMP7+ tumour cells was observed in both ST and bulk transcriptomics data, validated by multiplex immunofluorescence performed on 20 NSCLC samples." (PMID 39187937, 2024). "When compared to healthy individuals, the proportion of CD3+ cells in tumor patients' PBMC significantly dropped (P <0.0001), but the proportion of CD14+ cells and CD3-CD16+CD56+ cells remarkably increased (P <0.0001, P =0.0037)." (PMID 38911366, 2024). "The analysis revealed statistically significant correlations for survival post-tumor recurrence with the variables CD45+PD-L1+ (leukocyte cells positive for PD-L1) and CD45+CD11b+CD14+ PD-L1+ (TAMs positive for PD-L1)." (PMID 38791312, 2024). "To explore the characteristics of monocyte differentiation into TAM in CRC, we collected the tumor tissues of three CRC patients (WUH1, WUH2 and WUH3), and selected the marker gene CD14 for magnetic bead sorting (MACS)." (PMID 38408082, 2024). "In primary tumor stage I, we subclustered 1161 DCs into seven distinct subclusters, identifying subcluster 1 as activated DCs (n = 211 cells), subcluster 2 as CD163+CD14+ DCs (n = 191 cells), and subcluster 4 as pDCs (n = 145 cells)." (PMID 38612588, 2024). "CD14-positive cells are found only within the glial reactive tissue in ACP, whilst they are distributed throughout the tumour epithelium in PCP." (PMID 39127699, 2024). "The potential mechanism by which CX3CR1 influences CD14+ CD16− monocytes to facilitate the progression of PCa is through activation of the CX3CR1/CX3CL1 signalling pathway, promoting tumour angiogenesis, migration, and invasion." (PMID 39098992, 2024). "After characterizing CD1c+CD14+ cells in NSCLC, we directed our efforts to dissecting their development driven by tumor-derived factors." (PMID 38242119, 2024). "Monocytes, the main subpopulation of ‘classical’ CD14+CD16- monocytes, can differentiate into dendritic cells and macrophages, which can participate in the host’s anti-tumor response." (PMID 38327747, 2024). "Still, both CD14+ MDSCs and CD15+CD16+ mature neutrophils are known to be key hallmarks of tumor inflammation and immune suppression, subsets that are also involved in chronic infections." (PMID 38900571, 2024). "Next, we selected myeloid cell clusters on the basis of the expression of myeloid cell markers (“CD14+”, “FCER1A-”) by the scGate R package from GSE207422 (LUAD samples) and GSE205506 (CRC tumour samples)." (PMID 38773508, 2024). "The spatial co‐location of CD14+APOE+ cells and MMP7+ tumour cells was observed in ST data and further validated through multiplex immunofluorescence analysis conducted on 20 NSCLC samples." (PMID 39187937, 2024). "With increasing age, the proportion of CD3+ cells decreased overall, and the proportion of CD14+ and CD3-CD16+CD56+ cells increased, which was consistent with the influence of tumor on the proportion of immune cells compared with healthy individuals." (PMID 38911366, 2024).
tumor (continued). "This study identified immune exclusion and activation patterns in NSCLC and the co‐location of CD14+APOE+ cells and MMP7+ tumour cells as contributors to immune resistance." (PMID 39187937, 2024). "Aging, being male, and tumor metastasis exacerbated the difference in the number of CD3+ cells, CD14+ cells, and CD3-CD16+CD56+ cells between cancer patients and healthy participants." (PMID 38911366, 2024). "First, further validation in independent cohorts and prospective studies is necessary to confirm clinical utility of CD14+APOE+ cells and MMP7+ tumour cells." (PMID 39187937, 2024). "RT-qPCR showed expression of several macrophage markers in VS of which CD14, ALOX15, Interleukin-1β, INHBA and Colony Stimulating Factor-1R were found to have a high correlation with tumour volume." (PMID 38480935, 2024). "Consistent with this, the monocyte marker CD14 was expressed at low levels in the BLCA tissues relative to the paired normal tissues, while CD206 expression was high in the tumours." (PMID 38506082, 2024). "Moving to primary tumor stage II, we subclustered 232 DCs into four subclusters, with subcluster 3 representing CD163+CD14+ DCs (n = 48 cells)." (PMID 38612588, 2024). "The DC3 subpopulation, notable for CD14 and S100A9 markers, included 765 cells enriched within tumor samples." (PMID 38972873, 2024). "In an immunotherapy cohort from the ORIENT‐3 clinical trial, NSCLC patients who responded unfavourably exhibited higher infiltration of CD14+APOE+ cells and MMP7+ tumour cells." (PMID 39187937, 2024). "In future work, we plan to extend our research by incorporating animal models to experimentally validate the interactions between CD14+APOE+ cells and MMP7+ tumour cells." (PMID 39187937, 2024). "Subsequently, we assessed the capacity of tumour cells expressing MMP7 and CD14+ cells expressing APOE to forecast the effectiveness of treatment in patients undergoing immunotherapy." (PMID 39187937, 2024). "For CD14+ monocytes, the VEGFA/PGF-VEGFR1 axes play a significant role in tumor angiogenesis, and the EREG/AREG-EGFR communications serve as a critical factor in tumor proliferation in several solid human cancers." (PMID 38600248, 2024). "Over the course of our analysis of the M-MDCSs, defined as CD45+ LINneg (CD3, CD56, CD19) CD11b+CD33+CD14+HLA-DRdim/neg, in pts with CRC, we observed a significant increase in CD15+ monocytes in both the PB and tumor tissue." (PMID 39126041, 2024). "We next examined the expression of the markers identified previously that showed good correlation with tumour volume -ALOX15, IL-1β, CSFR1, CD14 and INHBA - to their expression at the single-cell level in the macrophage subclusters." (PMID 38480935, 2024). "However, the role of CD14 in tumor development may be more complex." (PMID 38566827, 2024). "With regard to tumor-promoting or immunosuppressive cells, CX3CR1 is reportedly expressed by Tregs, MDSCs, and TAMs; therefore, we analyzed CD3 expression in Tregs, CD14 and CD163 expression in M-MDSCs and TAMs, and LOX-1 expression in PMN-MDSCs." (PMID 38433196, 2024). "Experimental validation, such as functional assays or in vivo models, is required to definitively establish the mechanistic interactions between CD14+APOE+ cells and MMP7+ tumour cells in promoting immunotherapy resistance." (PMID 39187937, 2024). "We further aimed to identify tumour‐specific genes that induce CD14+APOE+ cells infiltration and exert immunosuppressive effects on the tumour TME." (PMID 39187937, 2024). "A distinct overexpression of CD1c, CD2, CD3, CD4, CD11c, CD14, CD20, CD44, CD56, CD105, CD146, and CD209 was identified in LCa patients compared to healthy controls, correlating positively with tumor presence." (PMID 38902710, 2024). "For CD14+ monocytes, the extracellular NAMPT contributes to tumor angiogenesis, decreased antitumor immunity, and resistance to ICBs50,51." (PMID 38600248, 2024).
tumor (continued). "For CD14+ monocytes, the VEGFA/PGF-VEGFR1 axes play a significant role in tumor angiogenesis, which is related to a poorer prognosis." (PMID 38600248, 2024). "According to clinical data, the tumor microenvironment responds to IL13Rα2 CAR T therapy by boosting CD3+, CD14+, and CD15+ immune cells as well as inflammatory cytokines after locoregional CAR infusion." (PMID 36721153, 2023). "We performed mIF staining of BrM tumor sections with CD3, CD14, CD206/MRC1, and α–smooth muscle actin (α-SMA), a major marker of brain blood vessels." (PMID 37655659, 2023). "The higher expression of CD68, CD163, CD206 on CD45/CD14+ cells in the 4-culture PANC-1 spheroids suggest a monocytes differentiation into M2-like macrophages, known to have tumor supporting functions." (PMID 37519820, 2023). "Tumor plasma cells were identified using a combination of markers including CD38, CD138, CD45, CD2, CD14, CD19 and CD56." (PMID 37046814, 2023). "High mtPCDI were broadly associated with higher levels of CD4 Naive, CD8 Effector, CD8 Naive, DC, Monocytes CD14, Monocytes CD16, NK, pDC, Plasma, and Th cells in the TCGA LGG developed for tumour characteristics." (PMID 37660060, 2023). "We observed that CD14+, CD68+, and CD163+ monocytes and CK+ tumor cells predominantly expressed LAIR-1 more than other cell types." (PMID 36960400, 2023). "Myeloid phenotypes with the highest fold changes between densely packed tumor cells and necrotic and perivascular areas were CD206+/CD14+/CD64+ (FC.404), CD206+/CD14+/CD64- (FC3.09), and TREM1+ (FC3.62)." (PMID 37694144, 2023). "When analyzing the tumor microenvironment of TRIM28-expressing NSCLC tumors, we observed an increase in CD14+ cells." (PMID 37865804, 2023). "In both tumors from this patient, over 80% of the cells in the tumor were myeloid cells, and the myeloid compartment shifted from high expression of CD163 to intermediate expression of CD14 and CD204 at resistance." (PMID 37620318, 2023). "Our panel includes CD11b and CADO as myeloid cell markers in addition to CD14 and MHC-II, which enables more precise detection of neutrophils and monocyte/macrophage subsets in canine tumor microenvironment." (PMID 36996049, 2023). "The spatial quantification of the immune cells using the GeoMx DSP technique revealed the significantly higher quantification of CD14 and CD163 in tumor regions of BM-LUAD as compared to BCBM." (PMID 37061716, 2023). "In tumor sections of mice treated with AT101, massive infiltration of both cells was detected, while signals corresponding to CD14 and CD56 expression were barely detectable in tumor sections of mice treated with the unspecific IgM." (PMID 38017492, 2023). "The HS of the CD16 + cells, Dendritic cells,pDC cells, B cells, and CD4 + Tconv cells in the tumor tissue were lower than those in normal tissue (P < 0.05), while NK cells, CD8 + cells, and CD14 + cells vice versa (P < 0.05)." (PMID 36627705, 2023). "Motivated by their findings, we simultaneously investigated the spatial heterogeneity in the TME cellular composition of CD14+ cells, CD19+ B cells, CD4+ and CD8+ T cells, and CK+ tumor cells, and their collective impact on the overall survival." (PMID 37756338, 2023). "The mean frequency of TAMs positive for CD14 or CD163 in the intratumoral stroma and CCL2+ tumor epithelial cells was higher in recurrences than in the corresponding primary tumors." (PMID 37208442, 2023). "A microfluidic size-based cell enrichment approach (ParsortixTM) was used for CAML detection, followed by immunofluorescence staining using pan-keratin, CD14, and CD45 antibodies to differentiate between CAMLs, circulating tumor cells (CTCs), and leukocytes." (PMID 36428523, 2022). "We showed that monocytes/macrophages identified as CD14+ cells highly infiltrate IBC cancer tissues and are localized with high density around IBC tumor emboli, clusters of highly metastatic IBC cells." (PMID 35847899, 2022).